CCL2 (C-C motif chemokine ligand 2)
Diseases named in the same sentence as CCL2 in open-access papers (continued):
Sharing a sentence is not in itself a finding about the gene and the disease.
endothelial dysfunction (200 papers, 2007 to 2025). In vascular diseases, endothelial dysfunction is a systemic pathological state of the endothelium (the inner lining of blood vessels) and can be broadly defined as an imbalance between vasodilating and vasoconstricting substances produced by (or acting on) the endothelium. "Although the clinical significance of these acute biomarker elevations remains uncertain, elevations in NfL and CCL-2 in other hypoxic or neurotrauma contexts have been associated with axonal stress, endothelial dysfunction, and microvascular permeability." (PMID 41586414, 2025). "The observed increase in permeability following treatment with hMC supernatant and rCCL2 confirms the role of CCL2 as a possible mediator of endothelial dysfunction." (PMID 39988712, 2025). "AS is initiated by endothelial dysfunction, which promotes secretion of chemotactic mediators such as CCL2 and chemokine (C-X-C motif) ligand 1 (CXCL1), recruiting circulating myeloid cells, particularly monocytes and neutrophils." (PMID 41583468, 2025). "In said context, PCSK9 deficiency reduces endothelial dysfunction by reducing the expression of lower endothelial expression of the genes encoding, e.g., ICAM-1, CCL2, IL-6 and IL-1β." (PMID 36361853, 2022). "We previously reported that abrogation of certain aspects of the secretome of senescent lung cells, in particular, signaling inhibition of the SASP-factor Ccl2/Mcp1 mediated radioprotection especially by limiting endothelial dysfunction." (PMID 34209135, 2021). "Our data not only suggest that ER stress induces transendothelial migration of leukocytes via upregulation of Icam1, Vcam1 and Ccl2 but it also involves O-glycosylation events suggesting a key role for PTMs in endothelial dysfunction." (PMID 31346222, 2019). "Moreover, during endothelial dysfunction, monocytes and their CX3CR1derivatives are recruited by MCP-1 to the site of inflammation promoted by the synthesis of MCP-1; CCL2 and c-Jun N-terminal kinases (JNK1 and JNK2) in adipose tissues and macrophages, respectively." (PMID 32069832, 2020). "The activated ACE2-Ang II axis can trigger macrophage infiltration and induce the secretion of several cytokines, including IL-6, CCL2, VCAM-1, and E-selectin, which induce endothelial dysfunction and, subsequently, coagulation." (PMID 35464491, 2022). "Studies have shown that the ACE2-Ang II axis can induce the infiltration of macrophages and secretion of certain cytokines, including IL-6, CCL2, vascular cell adhesion molecule 1 (VCAM-1), and E-selectin, to induce endothelial dysfunction, thrombin formation, and impaired fibrinolysis." (PMID 35464491, 2022). "As heightened inflammation is a key feature of endothelial dysfunction and PE, we selected two genes from the inflammation group, one up-regulated (IL6) and one down-regulated (CCL2) for validation at the protein level to further confirm the real-time RT-PCR data." (PMID 27780539, 2016).
liver fibrosis (199 papers, 2010 to 2026). "Our study establishes that myeloid-specific Tet2 deficiency exacerbates liver fibrosis through the Ccl2/Ccl8–pMDMs–IL-6–HSCs axis, with Tet2−/− pMDMs driving chemokine production, MDMs infiltration, and HSCs activation." (PMID 41474968, 2026). "mNOX-E36, a CCL2 inhibitor, can suppress the recruitment of MoMFs to the liver in CCl4-induced liver fibrosis models and methionine–choline-deficient diet (MCD)-induced NASH model." (PMID 41479922, 2025). "Mice deficient in GILZ show increased CCL2 production and pro-inflammatory leukocyte infiltration in early liver fibrosis, accelerating its progression." (PMID 39850880, 2024). "In these models, α7nAChR deficiency resulted in exacerbated hepatic fibrosis, higher plasma transaminase levels, and significantly increased Col1a1 gene-encoding alpha-1 type I collagen (mediating liver fibrosis) Ccl2 and Tnf gene expression." (PMID 31024226, 2019). "The important role of the CCL2-C-C motif chemokine receptor 2 [CCR2] signaling in liver fibrosis has been established in several experimental models using CCL2- or CCR2-deficient mice." (PMID 31805036, 2019). "Because DARC rs12075 SNP (125A > G; Asp42Gly) is a major determinant of circulating CCL2 levels and CCL2 has been associated with liver fibrosis progression, a relationship between rs12075 and liver cirrhosis is expected." (PMID 30970632, 2019). "For example, CCL2 polymorphism is found to be associated with significantly higher hepatic expression specifically in those individuals with advance liver fibrosis." (PMID 25528160, 2014). "Our study provides novel insights into how myeloid-specific Tet2 deficiency exacerbates liver fibrosis through the Ccl2/Ccl8–pMDMs–IL-6–HSCs axis, offering a potential therapeutic avenue for targeting fibrosis in populations with abundant aging individuals with TET2 mutations." (PMID 41474968, 2026). "It appears that CCL-2 upregulation is associated with nicotine-induced liver fibrosis in BDL rats." (PMID 38549169, 2024). "In NAFLD patients, serum levels of chemokines CCL2 was associated with inflammation and advanced hepatic fibrosis, FGF21 was associated with inflammation;In murine models of NASH, CCR2/5 inhibition reduced circulating Ly6C(hi) MoMFs, and the FGF21 agonist reduced body weight, hepatic triglycerides." (PMID 36875101, 2023). "In this study, the authors also found that the absence of melatonin synthesis enhanced the expression of biliary senescence markers, including p16, p21, C‐C motif chemokine ligand 2 (CCL2) and senescence‐associated β galactosidase (SA‐β‐gal), leading to hepatic fibrosis progression." (PMID 35404472, 2022). "Given that CCL2, an important factor associated with pathogenesis of both the viruses, it is important to understand the impact on liver cellular microenvironment and virus-triggered hepatic fibrosis." (PMID 25528160, 2014). "Inhibition of Ccl2 and Ccl8 by Bindarit effectively suppresses MDMs intrahepatic infiltration and ameliorates liver fibrosis in Tet2ΔMye-CCl4 mice, highlighting the critical role of these chemokines in fibrotic progression." (PMID 41474968, 2026). "In conclusion, Tet2ΔMye-induced myeloid hematopoiesis exacerbates liver fibrosis in both young and aging mice through a consistent Ccl2/Ccl8–pMDMs–IL-6–HSCs pathway highlighting a unified therapeutic target for age-associated fibrosis." (PMID 41474968, 2026). "Tet2ΔMye exacerbates liver fibrosis through stabilizing Ccl2/Ccl8 mRNAs in pMDMs, creating a chemokine-driven inflammatory loop." (PMID 41474968, 2026). "While our preclinical study demonstrates that Bindarit-mediated Ccl2/Ccl8 inhibition attenuates liver fibrosis in Tet2ΔMye-CCl4 mice, the discordance with cenicriviroc trial outcomes underscores the challenges of clinical application of our findings." (PMID 41474968, 2026). "The expression of TSC22D3 in liver biopsy samples of patients with liver fibrosis is negatively correlated with the expression of CCL2." (PMID 41262126, 2025).
liver fibrosis (continued). "For instance, SOCS1 in hepatocytes acts as a negative regulator, inhibiting CCL2 expression and subsequent monocyte infiltration to alleviate CCl4-induced hepatic fibrosis." (PMID 41479922, 2025). "This protective finding is also different to chronic hepatic injury models, such as CCl4-induced liver injury, where Sema7a promotes hepatic fibrosis and Il6 and Ccl2 expression." (PMID 40114253, 2025). "IFN-γ was mainly derived from CD8+ T cells and NK cells, and depletion of T cells or NK cells reduced IFN-γ, which resulted in improved hepatic inflammation and reduced CD8+ T-cell cytotoxicity, hepatic fibrosis, and CCL2 levels." (PMID 39859319, 2025). "In other fibrotic conditions such as liver fibrosis, CCL2 contributes to hepatic stellate cell activation, partially through TGF-β signaling." (PMID 40606673, 2025). "SMs enhance the secretion of CCL2 by hepatic macrophages, which in turn facilitates monocyte recruitment and the augmentation of liver fibrosis." (PMID 40977736, 2025). "Mφtgmif effectively ameliorates liver fibrosis and deactivates aHSCs by recruiting Ly6Chi macrophages via paracrine CCL2 and polarizing them into the restorative Ly6Clo macrophage through the secretion of CX3CL1." (PMID 38247166, 2024). "Activated HSCs secrete the monocyte chemoattractant protein‐1 (MCP1/CCL2) responsible for the infiltration of macrophages from the bone marrow, and plays a vital role in liver fibrosis progression." (PMID 38545255, 2024). "In the progress of liver fibrosis, peripheral pro-inflammatory mononuclear MoMφs can be attracted to the liver depending on CCL2/CCR2, CCL5/CCR5, and CCL1/CCR8 chemokines axis and aggravate liver fibrosis." (PMID 39635524, 2024). "The results showed that CCL2 blockade significantly hindered the treatment effects of BMDMstgmif on liver fibrosis." (PMID 38247166, 2024). "Then, an anti‐CCL2 antibody (4 μg per mouse, i.v.)or an equal amount of control antibody (IgG2b) was given to the liver fibrosis mice 3 h after cell infusion, and this procedure was repeated twice a week for two weeks." (PMID 38247166, 2024). "Kupffer cells play a role from the early stages of liver fibrosis; they sense the disruption of liver homeostasis and subsequently express chemokines such as CCL2 and CCL5." (PMID 39629085, 2024). "In liver fibrosis, CCL2 synergizes with TGF-β to activate hepatic stellate cells (HSCs) and promote matrix deposition." (PMID 39850880, 2024). "Suppressing the IL-33 signaling pathway can inhibit NASH progression by down-regulating CCL2 and α-SMA expression, while activating IL-19 signaling reduces HSC migration by down-regulating CCL2 expression, alleviating liver fibrosis." (PMID 39850880, 2024). "Monocyte chemoattractant protein-1 (CCL2) can mediate C-C chemokine receptor-2 (CCR2)+ macrophage infiltration to promote liver fibrosis." (PMID 37908726, 2023). "Previously, we studied the role of GILZ in a model of liver fibrosis (LF) showing how GILZ controls LF development by regulating CCL2-dependent leukocyte trafficking." (PMID 37815550, 2023). "Meanwhile, CCL2/CCR2 axis has also been implicated in the regulation of macrophage recruitment and polarization in the disease models of liver fibrosis and renal fibrosis." (PMID 37667317, 2023). "Increased liver MoMF infiltrate and liver fibrosis seen in opposite gain-of-function mice was ameliorated with concomitant hepatocyte Ccl2 knockout or CCR2 inhibitor treatment." (PMID 36752206, 2023). "To test repercussions of increased hepatocyte-derived MCP-1, we generated hepatocyte-specific Ccl2-knockout mice, which showed reduced liver MoMF infiltrate as well as decreased liver fibrosis." (PMID 36752206, 2023). "CCL2 is upregulated by hepatic monocytes during liver fibrosis, and production of CCL2 is elevated in both the serum and lungs of patients with pulmonary fibrosis." (PMID 37108548, 2023).
liver fibrosis (continued). "CCL2 is a key chemoattractant for macrophages, plays a crucial role in liver fibrosis and a potential therapeutic target." (PMID 37860002, 2023). "In a mouse model of liver fibrosis, CCL2 inhibitors prevented Ly-6Chi monocytes from entering the liver, thus indirectly increasing Ly-6Clo monocytes, and liver fibrosis was shown to significantly decrease." (PMID 37231461, 2023). "Our previous study demonstrated that splenic macrophages promoted chemokine CCL2 secretion in hepatic macrophages, facilitating monocyte recruitment and establishing an M1 dominant phenotype in hepatic macrophages, thus promoting hepatic fibrosis." (PMID 36159870, 2022). "Previous studies found that CCL2 secreted from hepatocytes triggered macrophage recruitment and induced liver fibrosis and even HCC." (PMID 33891564, 2021). "CCL2 has been proved to be the major chemokine for tumor-infiltrated immunosuppressive myeloid cells, such as TAMs and MDSCs, contributing to liver fibrosis, steatosis, and hepatocarcinogenesis." (PMID 34593796, 2021). "Since a study found some anti-fibrotic effects of CCL2 inhibitor in animal models of liver fibrosis, the pathway of CCL2/CCR2 as potential therapeutic targets should be further investigated by future studies." (PMID 33614685, 2021). "As the degree of liver fibrosis worsened, the expression of CCL2 gradually increased as compared to the control group (N group) (F1 vs. N, P = 0.013, F2 vs. N, P < 0.01, F3 vs. N, P < 0.001, F4 vs. N, P < 0.001)." (PMID 33614685, 2021). "The current study revealed the correlation between the high expression of CCL2, macrophage infiltration, and the hepatic fibrosis progress; the level of CCL2 strikingly increased with continuous activation of HSCs, which is essential in cirrhosis." (PMID 33614685, 2021). "To verify that CCL2 was responsible for macrophage infiltration and differentiation into M2 phenotype during liver fibrosis, we used rh CCL2 and its receptor antagonist INCB to confirm this pathway further." (PMID 33614685, 2021). "The M2 macrophage infiltration increased significantly with the progression of liver fibrosis, accompanied by the up-regulated expression of CCL2 in the fibrotic liver tissues." (PMID 33614685, 2021). "CCL2 and IL-8 act as chemoattractants, IL-6 is the major cytokine in acute phase response and osteopontin is a central mediator of liver fibrosis." (PMID 33003572, 2020). "For example, increase in serum levels of CCL2 is associated with progression from hepatic steatosis to NASH, and CCL2 expression is correlated with disease severity in Hepatitis C-dependent liver fibrosis." (PMID 33147210, 2020). "On the other hand, pharmacological inhibition of CCL2 accelerated fibrosis resolution in mouse models of liver fibrosis, thereby supporting the development of drugs targeting CCL2 receptors for NASH therapy." (PMID 33147210, 2020). "Immunofluorescence and western blot results showed that the expression of CCL2 was significantly increased in the liver tissues of CCl4-induced liver fibrosis mice and the distribution of CCL2 was mainly along the fibrous interval." (PMID 33293994, 2020). "Proinflammatory Ly6Chigh monocytes are recruited by CCL2, leading to further expansion of liver inflammation by releasing inflammatory factors and promoting the progression of liver fibrosis." (PMID 33293994, 2020). "Chemokines CCL2 and CXCL8 have been shown to play critical roles for recruitment of inflammatory cells and their expression has been linked to liver fibrosis." (PMID 32933544, 2020). "Activated KCs, HSCs, and injured hepatocytes all secrete high levels of CCL2, which exacerbates liver fibrosis by mediating the recruitment of inflammatory cells to the site of liver injury." (PMID 32492075, 2020). "In this review, we focus on the distinctive and complementary contributions of CCR5 and CCR2/CCL2 in HIV infection, multiple sclerosis, liver fibrosis and associated hepatocellular carcinoma." (PMID 31377844, 2019).
liver fibrosis (continued). "These B1 cells secrete IL-10, which inhibits expression of key chemokine CCL2 to limit excessive liver infiltration of Ly6Chi monocytes and thereby alleviate early inflammation and later liver fibrosis." (PMID 31194740, 2019). "Antibody-mediated depletion of CCL2 led to reduced immune cell infiltration to metastatic sites, while the use of CCL2 inhibitor reduced angiogenesis during liver fibrosis." (PMID 31350989, 2019). "In a mouse model of liver fibrosis and hepatocarcinogenesis, CCL2 inhibition by an RNA aptamer resulted in reduced TAM1 liver infiltrate and pathogenic angiogenesis, improvement of tissue fibrosis, and a significant inhibition of tumor progression." (PMID 31377844, 2019). "Over expression of TIMP-1 is associated whit liver fibrosis, while MMP-13 cleaves and inactivates CCL2, CCL7 and CXCL12 leading to reduction in chemotaxis, as well as to a decrease in the fibrosis process." (PMID 29040281, 2017). "The chemokine receptor CCR2 and its ligand MCP-1/CCL2 promote monocyte subset infiltration upon liver injury and further promote the progression of liver fibrosis." (PMID 26446682, 2015). "Upon injury, CCL2/CCR2 signaling induce infiltration of Ly6C+ inflammatory monocytes into the liver resulting in the promotion of liver fibrosis as well as angiogenesis." (PMID 25852818, 2015). "How these viruses communicate each other via chemokine CCL2 and exploit the liver specific cellular environment to exacerbate liver fibrosis in HIV/HCV co-infection setting is a topic of intense discussion." (PMID 25528160, 2014). "For instance, CCL2-dependent infiltrating macrophages derived from BM into the injured liver facilitate angiogenesis during the evolution of liver fibrosis through releasing pro-angiogenic factors including VEGF." (PMID 25162491, 2014). "To discuss the contribution of individual molecule in hepatic fibrosis is beyond the scope of this review thus herein, we focus on one of the most relevant mediator CCL2." (PMID 25528160, 2014). "By multiple linear regression using stepwise bidirectional selection, both candidate biomarkers, CCL-2 and sFasL, as well as race were independent predictors of hepatic fibrosis (p<0.007)." (PMID 23405244, 2013). "In contrast, serum levels of sFasL were significantly higher in patients with any form of hepatic fibrosis compared to those without it and increasing sFasL was a significant predictor of hepatic fibrosis even after controlling for race and CCL-2." (PMID 23405244, 2013). "By inhibiting CCL2 production in a bile duct ligated model of liver fibrosis in rats, HSC chemotaxis was markedly reduced." (PMID 23840855, 2013). "Several recent independent animal studies defined an important function of CCR2 and MCP-1/CCL2 for hepatic fibrosis." (PMID 20548789, 2010). "Independent studies highlighted the importance of the chemokine receptor CCR2 and its cognate ligand monocyte-chemoattractant protein 1 (MCP-1/CCL2) for monocyte recruitment during experimental hepatic fibrosis." (PMID 20548789, 2010). "Third, elevated levels of CCL2 and CCL8 were detected in the serum of elderly liver fibrosis patients carrying TET2 mutations, supporting the clinical relevance of a TET2–CCL2/8 regulatory axis in human disease, which provide a mechanistic basis for the potential clinical application of Bindarit." (PMID 41474968, 2026). "Furthermore, individuals with TET2Mut CHIP exhibited significantly more advanced liver fibrosis and relatively higher levels of Ccl2 and Ccl8 in serum compared with TET2 WT (TET2WT) counterparts, even after adjusting for co-occurring mutations." (PMID 41474968, 2026). "To investigate whether Tet2ΔMye in aging hosts exacerbates liver fibrosis through the Ccl2/Ccl8–pMDMs–HSCs axis, we established a competitive bone marrow transplantation (BMT) model using Tet2-deficient BMCs." (PMID 41474968, 2026).